MYC (MYC proto-oncogene, bHLH transcription factor)
Diseases named in the same sentence as MYC in open-access papers (continued):
Sharing a sentence is not in itself a finding about the gene and the disease.
cancer (continued). "A recent study demonstrated that PPi hubs can be identified for a variety of cancer-related genes, including MYC, STK11, RASSF1, and CDK4." (PMID 28362357, 2017). "Deregulated c-MYC expression is detected in most types of cancer including NSCLC and is often associated with aggressive, poorly differentiated tumors, which make c-MYC an attractive anti-cancer target." (PMID 28076844, 2017). "Our data support the notion that KRAS mutant cancer cells depend on the continued expression of MYC and drug-induced cytotoxicity of KRAS mutant cells is contingent on MYC inhibition." (PMID 28152508, 2017). "c-MYC is an oncogenic transcription factor that is overexpressed in many cancer types including B- and T-cell malignancies and is involved in cell metabolism and cell proliferation." (PMID 28724379, 2017). "As even subtle increases in MYC expression (>2 fold) can promote the cell and tissue overgrowth fundamental to cancer initiation and progression, these observations will have implications for human disease." (PMID 28398229, 2017). "MYC oncogene deregulation is observed in more than half of human cancers as a consequence of gene amplification, overexpression, chromosomal translocation, and/or protein stabilization." (PMID 28333115, 2017). "In this case, Yki nuclear accumulation was visible in the cancer tissue together with an upregulation of its target genes, including MYC." (PMID 28420161, 2017). "Nonetheless, the fact that HDAC inhibitors have already been exploited as therapeutic strategies for hematologic malignancies raises intriguing possibilities for further studies aiming at other cancer types expressing deregulated MYC." (PMID 28505071, 2017). "Taken together, our results reveal a previously unappreciated mechanism by which Menin functions as a regulatory factor that is critical for MYC-mediated transcription and cancer development." (PMID 28474697, 2017). "Past several decades have seen the rapid expansion in understanding the functions of MYC in cell growth and cancer progression." (PMID 28474697, 2017). "In this article, we review the role of MYC as a regulator of the cancer epigenome and transcriptome both through site-specific, local mechanisms as well as genome-wide effects, and highlight the potential for novel therapeutic strategies." (PMID 28505071, 2017). "While nuclear p27 acts as a break on the cell cycle by inhibiting CDK2 and MYC as discussed here, cytoplasmic p27 promotes cancer cell migration and invasion." (PMID 28665315, 2017). "It is expected that other cancer drivers beyond MYC can also be exploited in a similar manner to guide functional validation and therapeutic discoveries." (PMID 28205554, 2017). "is transcribed ∼60kb downstream of the MYC oncogene, and both reside within the 8q24 locus which undergoes copy number amplification in several cancers." (PMID 29113413, 2017). "Arguably, the role of the proto-oncogene MYC in drug resistance is one of the biggest unanswered questions concerning KRAS-driven cancers." (PMID 28152508, 2017). "Here, we discuss some of the findings that focus on the role of MYC in promoting cancer progression in three of the major breast cancer subtypes." (PMID 28696357, 2017). "Previous studies suggested that cancer cells possess traits reminiscent of the biological mechanisms ascribed to normal embryonic stem cells (ESCs) regulated by MYC and Polycomb repressive complex 2 (PRC2)." (PMID 28984200, 2017). "Here, surprisingly, we observed that, in cancer cells, Menin enhanced the expression of a large number of MYC target genes by interacting with MYC and P-TEFb." (PMID 28474697, 2017). "Glutamine was identified as the major respiratory fuel, while lactate derivation from both glucose and glutamine has been reported for MYC-dependent cancer cells." (PMID 28957320, 2017). "HDACs have been proven to have multiple functions in driving proliferation in high MYC-expressing cancers." (PMID 28505071, 2017).
cancer (continued). "By simplification, competition in cancer would be dictated by the global molecular changes of the cell, with c-MYC activity representing their algebraic sum." (PMID 28974715, 2017). "HDAC inhibitors, such as valproic acid (VA), trichostatin A (TSA), and suberoylanilide hydroxamic acid (SAHA), have come to light as effective therapeutic strategies for cancers characterized by high MYC expression." (PMID 28505071, 2017). "Among the gene expression networks known to influence the process of oncogenic transformation, the one controlled by the proto-oncogene MYC is one of the most frequently deregulated in cancer." (PMID 28704924, 2017). "Knockdown HDAC7 in multiple human cancer cell lines resulted in suppression of cell growth by down regulating c-MYC expression and up regulating p21 and p27 expression." (PMID 29126425, 2017). "Decades of attempts to therapeutically target MYC directly have not resulted in feasible clinical applications, and efforts have moved toward indirectly targeting MYC expression, function and/or activity to treat MYC-driven cancer." (PMID 28398229, 2017). "Overall, our data demonstrated that Menin enhanced the tanscriptional acitivity of MYC to promote cancer progression." (PMID 28474697, 2017). "MYC is a well-studied oncogene, with its respective protein being involved in the ability of cancer cells, as well as stem cells, to self-renew, and was lately proved to be PDK1-dependent in order to induce HEK cells transformation." (PMID 29064423, 2017). "We further elaborate on possible therapeutic interventions within this pathway as a potential new strategy to target MYC in cancer." (PMID 28665315, 2017). "CCAT2 was shown to promote cancer growth and metastasis and to increase MYC expression by enhancing TCF7L2 transcriptional activity." (PMID 28704924, 2017). "Splice mutations in Axin affecting its scaffolding function occur in some cancers, thereby impairing MYC degradation." (PMID 28665315, 2017). "The comparison of all cancer cell lines versus HCK1T revealed that MYCN as well as MYC were activated, and the majority of the downstream genes were upregulated." (PMID 28261610, 2017). "Additional approaches that exploit oncogene addiction are promising strategies against MYC-driven cancers." (PMID 28362357, 2017). "Despite the importance of MYC for cancer growth, it appears that the role of MYC in controlling growth during adult tissue homeostasis is limited." (PMID 28583252, 2017). "The 8q24 region represents one of the most frequently amplified cancer-associated regions in CRC, and contains the MYC oncogene." (PMID 28930145, 2017). "Our results have uncovered striking mechanistic similarities between growth of normal cells in culture, and growth of cancer cells in vivo by showing that MYC expression depend on the same genetic elements in cultured normal cells and in cancer cells." (PMID 28583252, 2017). "ODC1 itself was amplified in only 3% of cancers and had copy number gain in 13% often in the same cancers with MYC amplifications." (PMID 29240775, 2017). "Targeted therapy against 8q24 amplified cancers has remained challenging due to MYC being essential and in high abundance across normal tissue." (PMID 29113413, 2017). "Altered signaling cascades described so far involve deregulated transcription of target genes such as MYC and other cancer drivers." (PMID 29156698, 2017). "In this review, we have discussed the dual roles of MYC in the development of genomic instability and chemoresistance in cancer cells." (PMID 28590415, 2017). "EZH2, a HMT contributor to PRC2, is overexpressed in a variety of human cancers including those that express high MYC levels." (PMID 28505071, 2017). "The proto-oncogene MYC is over-expressed in many cancers and required by essentially all cancers for survival." (PMID 29321817, 2017).
cancer (continued). "By using a panel of previously well-characterized cancer-associated pathway reporter analyses, we found at least four pathways, e.g., ELK1/SRF, AP1, STAT1/2, MYC/MAX, are significantly affected." (PMID 28099902, 2017). "MYC was one of the most well-known deregulated oncogenes and the third most amplified gene in human cancer." (PMID 29084575, 2017). "The combination treatment also showed greater activity over single agents in inhibiting the phosphorylation of 4EBP1 and downregulation of the MYC protein level in different cancer models." (PMID 28362357, 2017). "Histone demethylase inhibitors target important KDMs in MYC-expressing cancers, such as LSD1 (KDM1) and KDM4." (PMID 28505071, 2017). "The transcription factor MYC (MYC proto-oncogene, bHLH transcription factor) is an essential signaling hub in multiple cellular processes that sustain growth of many types of cancers." (PMID 28696357, 2017). "Overexpression of MYC, an aggressive oncogene, is one of the most common drivers of human cancer and MYC dependent cell lines have remained resistant to therapeutics." (PMID 28558059, 2017). "c‐MYC controls more than 15% of genes responsible for proliferation, differentiation, and cellular metabolism in pancreatic as well as other cancers making this transcription factor a prime target for treating patients." (PMID 28275007, 2017). "We outline our current understanding of how MYC regulates chromatin structure in both a site-specific and genome-wide fashion, and highlight the implications for therapeutic strategies for cancers with high MYC expression." (PMID 28505071, 2017). "MYC (MYC proto-oncogene, bHLH transcription factor) expression is deregulated in various cancer types." (PMID 28696357, 2017). "MYC oncogene is overexpressed in >70% of human cancers and transcriptionally regulating cell cycle, cell death, senescence, cell adhesion, angiogenesis, genome stability, microenvironment, and metabolism." (PMID 28824643, 2017). "We also found groups of cancer cells dying when surrounded or adjacent to high MYC-expressing cells." (PMID 28974715, 2017). "Of note, there are accumulating lines of evidence that show that AURKA can regulate c‐MYC in cancer." (PMID 28417568, 2017). "Deregulation of such signaling pathways in cancer therefore frequently leads to deregulation of MYC expression." (PMID 28665315, 2017). "What possibilities are there to target the MYC/CDK2/SKP2/p27 axis in cancer, i.e., reducing the activity of MYC, CDK2 or SKP2, or boosting nuclear p27 expression?" (PMID 28665315, 2017). "In future experiments, it would be interesting to explore the potential beneficial effect of targeting and reducing TDRD3 expression in cancers known to be ‘addicted’ to MYC over-expression." (PMID 28698590, 2017). "This evidence clearly suggests that, in advanced cancer cells, oncogenic MYC develops a highly efficient DNA repair system and offsets the genomic instability induced by chemo and radiation therapy." (PMID 28590415, 2017). "MYC is a master transcriptional factor that increases catabolism and is deregulated in numerous human cancers." (PMID 28872614, 2017). "Further expanding the list of chromatin modifying enzymes that MYC is known to regulate in the context of cancer, the direct control of the DNA methylating machinery reveals a novel facet of MYC’s global reach." (PMID 29100357, 2017). "One of the most common attributes of successful MYC inhibition in cancer cells is the depletion of intracellular ATP." (PMID 28362357, 2017). "We further demonstrate that, by transcriptionally promoting the expression of MYC target genes in cancer cells, Menin stimulates cell proliferation and cellular metabolism both in vitro and in vivo." (PMID 28474697, 2017).
cancer (continued). "Overexpression of MYC oncogenes found in many cancers was shown to silence the circadian clock in different types of tumors." (PMID 28425940, 2017). "The fact that elevated levels of MYC proteins are found in 60–70% of all cancers and the discovery that tumors can be dependent on continuous MYC expression (known as oncogene addiction) have made this family of oncogenes a highly promising therapeutic target." (PMID 28505071, 2017). "Although the regulation of GLS1 in cancer cells is not well understood, several studies indicate a functional link between the oncogene MYC and glutamine metabolism." (PMID 28399896, 2017). "Cancer cells become reliant on the MYC-induced changes that occur in proliferation, metabolism, DNA repair, RNA splicing, and survival." (PMID 28362357, 2017). "Although MYC is clearly required for the maintenance of KRAS-driven cancer, our data imply that the KRAS oncogene is inefficient in sustaining expression of MYC in the absence of growth factors or in response to anticancer drug treatment." (PMID 28152508, 2017). "We single out below three metabolic pathways, which are altered by MYC and which represent the metabolic phenotype of many types of cancer cells." (PMID 28443281, 2017). "Subsequent studies showed that SKP2 participates in the regulation of subsets of MYC target genes of importance for proliferation and cancer development." (PMID 28665315, 2017). "Their powerful oncogenic fame derives from their frequent deregulation in a myriad of human cancers and from a series of activities that place MYC at the nexus of cell growth, proliferation, metabolism, and genome stability." (PMID 28327152, 2017). "There is some evidence to suggest that MYC acts indirectly through other transcription factors to influence the degree of glycolysis within cancer cells." (PMID 28362357, 2017). "Since MYC protein is refractory to small-molecule inhibition, the dependence of high MYC protein levels on PVT1 lncRNA suggests a promising way to therapeutically target this protein in MYC-positive cancers." (PMID 29165379, 2017). "The tightly controlled expression of MYC, its short half-life, and critical role in normal cell metabolism makes direct targeting of MYC a challenge for anti-cancer therapeutics." (PMID 28362357, 2017). "VPS9D1-AS1 expression is not limited to CRC cell lines but it is a feature also of other cancer cell lines with high MYC expression." (PMID 28704924, 2017). "For instance, genetic or pharmacological inhibition of the spliceosome in vivo was shown to associate with an impair in survival, tumourigenicity, and metastatic proclivity of MYC-dependent cancers." (PMID 28374191, 2017). "More recently, strategies targeting epigenetic “readers” in cancers that harbor MYC overexpression have received much attention." (PMID 28505071, 2017). "Paradoxically, oncogenic MYC can also promote the resistance of cancer cells to chemotherapeutic DNA-damaging agents such as cisplatin, clearly implying an antagonistic role of MYC in genomic instability." (PMID 28590415, 2017). "The second network, involved in cancer, has MYC as the central node (score = 144.3), followed by CDKN1A (score = 119.5) and FOS (score = 118.4)." (PMID 29216278, 2017). "Exploiting metabolic vulnerabilities of MYC-driven cancers is an emerging research area with translational potential." (PMID 28362357, 2017). "MYC is both upstream and downstream of metabolism and thus is centrally relevant as a target in cancer therapy." (PMID 28362357, 2017). "BRG1 is a tumor suppressor in most cancer types, but it promotes MYC transcription and maintains oncogenic programming in leukemia cells." (PMID 28212646, 2017). "Because of the strong correlation between MYC overexpression and tumorigenesis, it is anticipated that survival of cancer cells would be greatly compromised if MYC is inactivated." (PMID 28590415, 2017).
cancer (continued). "HIFs also operate in conjunction with oncogenic MYC, an oncogene overexpressed in about 30% of human cancers and known to upregulate glycolytic enzymes such as LDH." (PMID 28337200, 2017). "The obtained prediction of antipodal effects of KRAS and MYC induction on the drug sensitivity of cancer cells was then tested experimentally." (PMID 28152508, 2017). "Tseng60 indicated that high MYC protein levels in 8q24-amplified human cancer cells require gain of PVT1 expression to suppress phosphorylation of T58, in turn protecting MYC protein from degradation." (PMID 28389669, 2017). "In embryonal rhabdomyosarcoma cell lines, MYC protects cancer cells from radiation-induced apoptosis and DNA damage, while promoting radiation-induced DNA repair." (PMID 28590415, 2017). "There are several potential ways by which cancer cells deregulate MYC, leading all to overexpression of MYC proteins and their disconnection from the critical signalling processes that normally keep it in check." (PMID 28327152, 2017). "Intriguingly, both MYC Ser-62 and Thr-58 mutant mice displayed genomic instability, but only MYC Thr-58 mutant mice developed carcinomas." (PMID 28665315, 2017). "Treatment of a panel of human carcinoma cell lines with VLX600 resulted in a strong reduction in MYC levels in 4/5 cell lines tested." (PMID 29163823, 2017). "Of interest, while E1A 1-80 repression of MYC occurs in all eight human cancer cell lines examined, repression of HER2 is cell-type dependent." (PMID 27382434, 2016). "Although we observed a trend toward increased MYC in cancer compared to adjacent normal, the difference in average expression of MYC was not statistically significant between these two groups." (PMID 27232880, 2016). "MYC expression is dysregulated in many human cancers by either chromosomal translocation or gene amplification." (PMID 28040803, 2016). "We also found ITH in the transcriptome; notably, the major subclone harboring MYC amplification showed upregulation of the MYC expression signature together with other signatures related to cancer malignancy." (PMID 26890883, 2016). "c-MYC activity is frequently altered in GBMs and, like hypoxia, is associated with maintenance of GBM cancer stem cells." (PMID 27119353, 2016). "Ectopic expression of c-MYC suffices to induce metastasis in a murine non-small-cell lung cancer (NSCLC) model featuring the most lethal human cancer due to its high metastasis rate." (PMID 27313991, 2016). "MYC overexpression is common to the majority of human cancers, yet attempts to directly target this oncogene as a therapeutic strategy have historically proven challenging." (PMID 27590350, 2016). "Previous reports have shown that PVT1 stabilizes MYC protein levels, promoting cell proliferation in cancer." (PMID 27366943, 2016). "The oncogenetic activity of MYC is altered by Bortezomib treatment to induce cancer cell death by enhancing expression of the pro-apoptotic BCL2 family members NOXA and BIM." (PMID 26683226, 2016). "A better understanding of the relationship between E2F2 and MYC in various cancer contexts remains for future study." (PMID 27081696, 2016). "Although Omomyc cannot penetrate human tumors and hence is ineffective as a cancer therapeutic, it has proven useful to explore the consequences of MYC inhibitionin vivo." (PMID 27081479, 2016). "In contrast with many other cancers, copy-number gains at the MYC locus are relatively infrequent in ccRCC18." (PMID 27774982, 2016). "Here, MYC silencing is able to reduce cancer cell proliferation, invasion and migraion in vitro in agreement with previous studies." (PMID 27863420, 2016).